COMMD4 (COMM domain containing 4)
Description:
Scaffold protein in the commander complex that is essential for endosomal recycling of transmembrane cargos; the commander complex is composed of the CCC subcomplex and the retriever subcomplex. May modulate activity of cullin-RING E3 ubiquitin ligase (CRL) complexes. Down-regulates activation of NF-kappa-B.
Synonyms: FLJ20452
Tractability: Antibody: its Gene Ontology location is reachable by antibodies, with high confidence. PROTAC: ubiquitination databases record sites on it; its protein half-life has been measured.
Gene: Protein-coding gene on chromosome 15 (75,336,009 to 75,343,224, forward strand). Ensembl gene ENSG00000140365.
Subcellular location: Cytoplasm; Nucleus
Subcellular location (Human Protein Atlas): Cytosol; Plasma membrane; Vesicles
Pathways (Reactome):
Metabolism of proteins: Neddylation
Gene Ontology:
Molecular function: protein binding
Biological process: endocytic recycling; signal transduction
Cellular component: cytoplasm; cytosol; nucleus; protein-containing complex; endoplasmic reticulum membrane; endosome membrane
Genetic constraint (gnomAD): Loss-of-function variants: 18 observed, 27.19 expected, observed/expected ratio (o/e) 0.66, 90% interval 0.46 to 0.98. The upper end of that interval is the gene's LOEUF score, 0.98, which puts it in group 4 of 6, group 1 being the genes least tolerant of losing a copy. Missense variants: 243 observed, 248.16 expected, observed/expected ratio (o/e) 0.98, 90% interval 0.88 to 1.09. Synonymous variants: 108 observed, 104.16 expected, observed/expected ratio (o/e) 1.04, 90% interval 0.89 to 1.22.
Homologues: Orthologues: macaque COMMD4 (97% identical), pig COMMD4 (94% identical), chimpanzee COMMD4 (91% identical), mouse Commd4 (90% identical), rat Commd4 (89% identical), dog COMMD4 (88% identical), guinea pig COMMD4 (87% identical), zebrafish commd4 (66% identical), tropical clawed frog commd4 (59% identical), Drosophila melanogaster CG34039 (34% identical), Caenorhabditis elegans T28F2.2 (23% identical).
Diseases named in the same sentence as COMMD4 in open-access papers:
COMMD4 is named in the same sentence as 11 diseases in open-access papers, as found by Europe PMC text mining. Sharing a sentence is not in itself a finding about the gene and the disease. The quoted sentences say what the papers report.
lung cancer (5 papers, 2020 to 2024). A malignant neoplasm involving the lung. "In non‐small cell lung cancer (NSCLC) cells, COMMD4 expression is increased, and siRNA‐mediated COMMD4 knockdown reduces cell proliferation, migration, and viability." (PMID 36205192, 2023).
non-small cell lung carcinoma (5 papers, 2020 to 2024). A group of at least three distinct histological types of lung cancer, including non-small cell squamous cell carcinoma, adenocarcinoma, and large cell carcinoma. "Higher expression of COMMD4 has been found in non-small cell lung cancer (NSCLC), and was associated with poor prognosis in adenocarcinoma (ADC)." (PMID 34493238, 2021). "Following COMMD4 knockdown, non-small cell lung cancer (NSCLC) cells experienced mitotic catastrophe and apoptosis." (PMID 36249824, 2022). "The authors demonstrated that COMMD4 depletion resulted in the induction of mitotic catastrophe and apoptosis of non-small cell lung cancer cells." (PMID 34307454, 2021). "A recent player in the DSB repair pathway, COMMD4, has shown promise as a potential prognostic marker and therapeutic target in non-small cell lung cancer." (PMID 34307454, 2021).
breast carcinoma (2 papers, 2021 to 2023). "We found that METTL3 depletion promoted exon inclusion of the alternative exons of GNAS, MATR3, POLDIP3 and promoted skipping of the alternative exons of COMMD4, MARK3 and the non-m6A modified transcripts FASTK and EXOC7 in both breast cancer cell lines." (PMID 36725888, 2023). "Taken together, the AS events analyzed in COMMD4_AS2, EXOC7, RHOC, COMMD4_AS1 and POLDIP3 were related to a worse breast cancer prognosis, and could constitute potential prognosis biomarkers." (PMID 36725888, 2023). "We observed that the AS events for COMMD4_AS2, GNAS, MATR3,COMMD4_AS1 and RHOC displayed a significant higher PSI value in cancer patients than in normal samples, while the PSI values were significantly lower for MARK3, POLDIP3 and FASTK in patients with breast cancer." (PMID 36725888, 2023).
glioblastoma (2 papers, 2022 to 2025). The most malignant astrocytic tumor (WHO grade IV). "COMMD4 expression is associated with poor prognosis in several cancers, including NSCLC and glioblastoma, influencing tumor proliferation, invasion, metastasis, and drug resistance." (PMID 40739397, 2025). "Factors such as COMMD4 expression (p < 0.001), histology (astrocytoma, oligodendroglioma, Glioblastoma) (p < 0.05), grade (WHO grade) (p < 0.001), chemotherapy (p < 0.001), IDH mutation (p < 0.001) and 1p19qcodeletion (p < 0.001) were determined premised on the univariate analysis." (PMID 36249824, 2022). "In this study, COMMD4 expression was upregulated in siPFKFB4, siHMOX1, and DOX alone groups, explaining glioblastoma cells’ resistance to treatment." (PMID 40739397, 2025).
glioma (1 paper, 2022). A benign or malignant brain and spinal cord tumor that arises from glial cells (astrocytes, oligodendrocytes, ependymal cells). "With the two CGGA datasets, an integrative survival analysis was performed to examine the association of COMMD4 expression with survival of glioma patients." (PMID 36249824, 2022). "The elevated COMMD4 expression level was linked to greater glioma malignancy, according to the findings." (PMID 36249824, 2022). "The TIMER database was used to investigate whether the immune infiltration levels in glioma were linked to the COMMD4 expression levels." (PMID 36249824, 2022). "COMMD4 level was elevated in gliomas and COMMD4 was associated with tumor grade." (PMID 36249824, 2022). "GSEA was used to conduct GO terms and KEGG pathway analyses to further examine the possible biological roles of COMMD4 in glioma." (PMID 36249824, 2022). "In Dataset 1 (ID: mRNAseq 325), patients in the high-COMMD4 expression group with primary glioma demonstrated an unfavorable prognosis (p < 0.001)." (PMID 36249824, 2022). "The elevated expression levels of COMMD4 accelerated the malignant progression of glioma, as evidenced by the IDH1-wildtype patients’ unfavorable survival." (PMID 36249824, 2022). "GSEA and drug response analysis revealed the potential mechanism of COMMD4 in drug resistance of glioma." (PMID 36249824, 2022). "This investigation proved the significance of COMMD4 in the pathogenesis of glioma, identified a new possible therapeutic target for glioma treatment and a prognostic indicator." (PMID 36249824, 2022). "The level of COMMD4 expression in paraneoplastic tissue and tumor tissue from glioma patients was initially examined in this research." (PMID 36249824, 2022). "We then examined the relationship between infiltration levels of immune cells in glioma and COMMD4 expression." (PMID 36249824, 2022). "This research improves the current understanding of the mechanisms and functions of COMMD4 in glioma." (PMID 36249824, 2022). "According to the RT-qPCR data, the expression of COMMD4 was up-regulated in glioma tissues relative to adjoining tissues." (PMID 36249824, 2022). "In LGGs and GBMs, patients diagnosed with glioma exhibited low survival rate and elevated COMMD4 expression level." (PMID 36249824, 2022). "Thus, additional research was encouraged to identify COMMD4 as a viable prognostic marker in glioma treatment resistance." (PMID 36249824, 2022). "This research examined whether the copper-metabolism-domain protein, COMMD4, had predictive and therapeutic significance in glioma." (PMID 36249824, 2022). "In both datasets, comparable associations between COMMD4 expression levels and WHO glioma grades could be found." (PMID 36249824, 2022). "Furthermore, we compared chemotherapy and radiotherapy to highlight the role of COMMD4 and identified COMMD4 as a molecular marker for glioma patients’ prognosis." (PMID 36249824, 2022). "Although the mechanisms of COMMD4 in glioma cells are unknown, various research reports have shown that it is intimately linked to tumor genomic stability and apoptosis." (PMID 36249824, 2022). "In glioma development, high COMMD4 expression level might affect mechanisms of treatment resistance and tumor immunology." (PMID 36249824, 2022). "Furthermore, a high level of COMMD4 overexpression was related to an unfavorable prognosis and impaired infiltration of immune cells in glioma." (PMID 36249824, 2022). "Meanwhile, qRT-PCR was conducted to examine COMMD4 expression in human glioma." (PMID 36249824, 2022). "In summary, this is the first research exploring the function of COMMD4 in glioma." (PMID 36249824, 2022). "Nonetheless, it is unknown if COMMD4 could be employed as a biological marker for glioma and its involvement in gliomas is also unclear." (PMID 36249824, 2022).
glioma (continued). "We hypothesized that elevated COMMD4 expression level had a pivotal regulatory function in these oncogenic pathways, and this resulted in a poorer prognosis for glioma patients." (PMID 36249824, 2022). "Finally, the primary glioma pathway mediated by COMMD4 may be connected to genomic stability, which may be associated with glioma treatment resistance." (PMID 36249824, 2022). "In addition, qRT-PCR verified the high expression of COMMD4 in glioma tissues and cells." (PMID 36249824, 2022). "Furthermore, qRT-PCR confirmed the high expression of COMMD4 in glioma tissues and cells." (PMID 36249824, 2022). "Though the association between COMMD4 and glioma was not yet completely clarified, it could be speculated that COMMD4 influenced the development of pathophysiological pathways of glioma based on our findings and previous research on COMMD4." (PMID 36249824, 2022). "Our findings suggested that the negative impact of COMMD4 on glioma could be resulted from the reduced density of mast cells." (PMID 36249824, 2022).
hepatocellular carcinoma (1 paper, 2022). A malignant tumor that arises from hepatocytes. "COMMD4 is a protein-coding gene belonging to the COMMD family, and is expressed at a high level in non-small cell lung cancers (NSCLC) and hepatocellular carcinoma (HCC)." (PMID 36249824, 2022).
cancer (8 papers, 2020 to 2025). A tumor composed of atypical neoplastic, often pleomorphic cells that invade other tissues. "COMMD4 plays a critical role in cancers, functioning to allow genetically unstable cancer cells to survive by limiting excessive remodelling of chromatin and dampening DNA damage-induced cell signalling and apoptosis." (PMID 37914802, 2023). "We suggest that loss of functional COMMD4 in NSCLC cell lines results in uncontrolled chromatin remodelling due to their inherent genetic instability, a universal hallmark of cancer." (PMID 37914802, 2023). "The authors demonstrated that depletion of COMMD4 in non-small lung cancer patient cell lines impaired proliferation of these cells and resulted mitotic catastrophe and cancer cell death." (PMID 33875784, 2021). "In order to investigate the role of COMMD4 in NSCLC, the expression of COMMD4 gene transcripts were first evaluated using bioinformatic analysis of The Cancer Genome Atlas (TCGA) datasets." (PMID 32439936, 2020). "We show that in NSCLC patient cell lines, COMMD4 plays a vital role in mediating cancer cell proliferation and the depletion of COMMD4 impairs the proliferation of these cells." (PMID 32439936, 2020). "H2B peptide directly binds to COMMD4 and inhibits its interactions, thereby increasing sensitivity to radiotherapy by causing DNA DSBs accumulation and mitotic catastrophe, suggesting COMMD proteins are potential targets for cancer therapy." (PMID 38871970, 2024). "Since the COMMD family members COMMD1 and COMMD4 had been reported to be involved in DNA damage repair to maintain the genome stability of the cancer cells, we wondered whether COMMD10 plays a role in DNA damage in GC cells." (PMID 38871970, 2024). "We speculate that COMMD4 may become a therapeutic target for the treatment of cancer." (PMID 33875784, 2021). "Additionally, COMMD4 is a potential therapeutic target for NSCLC, as its depletion induces cancer cell death." (PMID 32439936, 2020).
tumor (5 papers, 2020 to 2025). "While in other organs with less toxic, higher expression of COMMD4 means that tumor cells have already accumulated more toxic substances." (PMID 34493238, 2021). "Within the ADC NSCLC tumours expressing COMMD4 in the nucleus, 27% of cases exhibited weak staining." (PMID 32439936, 2020). "Meanwhile, a link between COMMD4 and many tumor-infiltrating immune cells was observed." (PMID 36249824, 2022). "Within the SCC NSCLC tumours expressing COMMD4 in the nucleus, 8% of cases exhibited weak staining." (PMID 32439936, 2020). "We speculated that COMMD4 may have certain effects on tumor immunity." (PMID 36249824, 2022). "Therefore, in HCC cells, higher expression of COMMD4 may mean stronger genomic stability for tumor cell proliferation and stronger toxic adaptive capacity." (PMID 34493238, 2021). "Our TMA analysis was consistent with our mRNA analysis and demonstrated that COMMD4 expression was high regardless of age, tumour grade, surgical stage or TNM score." (PMID 32439936, 2020).
adenocarcinoma (3 papers, 2020 to 2022). A common cancer characterized by the presence of malignant glandular cells. "Bioinformatic analysis and in vitro analysis of COMMD4 transcripts showed that COMMD4 levels were upregulated in NSCLC and elevated COMMD4 was associated with poor prognosis in adenocarcinoma (ADC)." (PMID 32439936, 2020). "Meanwhile, higher expression of COMMD4 has been found in NSCLC and was linked to unfavorable prognosis in adenocarcinoma (ADC)." (PMID 36249824, 2022).
COMMD4 also shares sentences with these, for which no sentence is quoted: astrocytoma (1 paper); oligodendroglioma (1).